PLOD1 (procollagen-lysine,2-oxoglutarate 5-dioxygenase 1)
Description:
Part of a complex composed of PLOD1, P3H3 and P3H4 that catalyzes hydroxylation of lysine residues in collagen alpha chains and is required for normal assembly and cross-linkling of collagen fibrils (By similarity). Forms hydroxylysine residues in -Xaa-Lys-Gly-sequences in collagens. These hydroxylysines serve as sites of attachment for carbohydrate units and are essential for the stability of the intermolecular collagen cross-links (Probable).
Synonyms: LH1; LLH; PLOD; EDS6; EDSKCL1; LH
Tractability: Antibody: UniProt places it where antibodies can reach, with medium confidence; UniProt predicts a signal peptide or a membrane-spanning region; its Gene Ontology location is reachable by antibodies, with medium confidence. PROTAC: ubiquitination databases record sites on it; its protein half-life has been measured; a small molecule that binds it is known.
Target class: Enzyme; Oxidoreductase
Gene: Protein-coding gene on chromosome 1 (11,934,205 to 11,975,542, forward strand). Ensembl gene ENSG00000083444.
Subcellular location: Rough endoplasmic reticulum membrane
Subcellular location (Human Protein Atlas): Vesicles; Nucleoplasm
Pathways (Reactome):
Extracellular matrix organization: Collagen biosynthesis and modifying enzymes
Gene Ontology:
Molecular function: procollagen glucosyltransferase activity; procollagen-lysine 5-dioxygenase activity; protein binding; iron ion binding; L-ascorbic acid binding; oxidoreductase activity, acting on paired donors, with incorporation or reduction of molecular oxygen
Biological process: collagen biosynthetic process; epidermis development; protein O-linked glycosylation; response to hypoxia; collagen fibril organization
Cellular component: extracellular exosome; endoplasmic reticulum; endoplasmic reticulum membrane; extracellular matrix; Golgi apparatus; catalytic complex; rough endoplasmic reticulum membrane
Genetic constraint (gnomAD): Loss-of-function variants: 57 observed, 75.77 expected, observed/expected ratio (o/e) 0.75, 90% interval 0.61 to 0.94. The upper end of that interval is the gene's LOEUF score, 0.94, which puts it in group 3 of 6, group 1 being the genes least tolerant of losing a copy. Missense variants: 858 observed, 942.73 expected, observed/expected ratio (o/e) 0.91, 90% interval 0.86 to 0.96. Synonymous variants: 402 observed, 387.01 expected, observed/expected ratio (o/e) 1.04, 90% interval 0.96 to 1.13.
Homologues: Orthologues: chimpanzee PLOD1 (97% identical), dog PLOD1 (94% identical), rabbit PLOD1 (92% identical), macaque PLOD1 (92% identical), pig PLOD1 (92% identical), mouse Plod1 (91% identical), rat Plod1 (91% identical), guinea pig PLOD1 (91% identical), tropical clawed frog plod1 (70% identical), zebrafish plod1a (67% identical), Drosophila melanogaster Plod (44% identical), Caenorhabditis elegans let-268 (43% identical). Paralogues in human: PLOD2 (60% identical), PLOD3 (59% identical), COLGALT1 (19% identical), COLGALT2 (17% identical), CERCAM (17% identical).
Diseases named in the same sentence as PLOD1 in open-access papers:
PLOD1 is named in the same sentence as 106 diseases in open-access papers, as found by Europe PMC text mining. Sharing a sentence is not in itself a finding about the gene and the disease. The quoted sentences say what the papers report.
breast carcinoma (19 papers, 2014 to 2025). "In breast cancer tissues, the total immunostaining score of PLOD1 expression was significantly associated with the ER status (P = 0.04384), the TNBC status (P = 0.01592) and tumor grade (P = 0.001192)." (PMID 39068670, 2024). "High PLOD1 expression predicts poor overall and DFS in multiple cancers, including breast cancer), and PLOD1 inhibition (via siRNA or small molecules) attenuates proliferation, migration, and invasion in bladder cancer and glioma models." (PMID 41373732, 2025). "PLOD1 expression was increased in breast tumors compared to normal breast tissues, promoted lymph node, and lung metastasis, and its expression in breast cancer cells was induced by hypoxia." (PMID 38417630, 2024). "For instance, hypoxia-induced factor-1 activates PLOD1 in breast cancer, and to a great extent, activates PLOD2 in cancer development." (PMID 34646265, 2021). "Overexpression PLOD1 promoted proliferation of breast cancer and lymph node and lung metastasis through regulating collagen cross-linking." (PMID 33420370, 2021). "Hypoxia-inducible factor-1α also regulates PLOD1 transcription in breast cancer; however, PLOD2 activity is more critical for HIF-1-induced cancer progression." (PMID 30770789, 2019). "Our study suggests that patients expressing high levels of PLOD1 can be targeted for therapies against prolyl 4-hydroxylase alpha subunits pending confirmation that an increase in PLOD1 mRNA results in increases in PLOD1 protein levels in breast cancer patients." (PMID 41373732, 2025). "GIs between MEMO1 and PLOD1 in breast cancer cells that we found are particularly notable." (PMID 38640016, 2024). "ACO1, SLC25A28, and PLOD1 showed GOF interactions with MEMO1 in breast cancer cells." (PMID 38640016, 2024). "Overexpression of PLOD1 was also detected in esophageal squamous cell carcinoma and breast cancer." (PMID 31199049, 2019). "Noteworthy, PLOD1, mediating crosslinking of collagen fibers, is the only commonly up-regulated gene in both IDHmut and IDH1wt GSCs under hypoxia and has shown to be regulated by HIF1alpha in breast cancer cells leading to increased invasion and metastasis." (PMID 30257451, 2018). "PLOD1, the only commonly up-regulated gene in IDH1mut and IDH1wt GSCs under hypoxia, mediates crosslinking of collagen fibers and has shown to be regulated by HIF1alpha in breast cancer cells leading to increased invasion and metastasis." (PMID 30257451, 2018). "In addition, hypoxia-inducible factor 1 (HIF-1) also activates transcription of PLOD1 in breast cancer cells; however, function PLOD2 is more important for HIF-1-induced cancer progression." (PMID 30003082, 2018). "Five proteins (LMAN1, AZI2, STAU2, MMP9 and PLOD1) from a systemic analysis of a variety of array data of breast cancer patients were subjected to immunofluorescence staining to evaluate the presence of fixed WBCs on 96-well plates from 363 healthy females and 358 female breast cancer patients." (PMID 33441653, 2021). "Using UALCAN in TCGA, we discovered that PLOD1 and PLOD3 were significantly upregulated in breast cancer tissues compared to normal tissues." (PMID 39068670, 2024). "Activation of PLOD1 and PLOD2 at the transcription level by HIF-1 is required for biogenesis of collagen in breast cancer cells." (PMID 31308057, 2019). "Although HIF-1 induces expression of PLOD1 and PLOD2, PLOD2 expression in breast cancer cells is more important for fibrillary collagen formation, tumor stiffness and cancer metastasis to lymph nodes and lungs." (PMID 30003082, 2018). "Analysis of the gene expression levels in multiple breast cancer cell lines revealed weak but statistically highly significant correlations between the levels of MEMO1 and TFR1 (p=4.6E-18), TFR2 (p=1.8E-14), and PLOD1 (p=1.8E-33)." (PMID 38640016, 2024). "We found PLOD1 and PLOD3 were highly expressed in breast cancer tissues and in all stage subgroups." (PMID 39068670, 2024).
breast carcinoma (continued). "Finally, KM Plotter analysis of the hub genes showed that the high expression of ADM, ENO1, PLOD1, and CEBPB was significantly correlated with a shorter OS and poor prognosis in patients with breast cancer." (PMID 37391802, 2023). "Moreover, it has been reported that in breast cancer, HIF-1 activates PLOD1 and PLOD2 transcription under hypoxic conditions, regulates collagen cross-linking, and promotes lymph node and lung metastasis." (PMID 33420370, 2021). "PLOD1 and PLOD2 expression was induced by hypoxia in breast cancer cells." (PMID 31231467, 2019). "Remarkably, ACO1 knockdown only inhibited proliferation of the high-MEMO1 cells, but not MEMO1 knockout breast cancer cells, while SLC25A28 and PLOD1 knockdowns showed some effect in all cell lines, but a stronger inhibition in the high-MEMO1 cells than in MEMO1 knockout." (PMID 38640016, 2024).
Ehlers-Danlos syndrome (16 papers, 2011 to 2025). The Ehlers–Danlos syndromes (EDS) are a clinically and genetically heterogeneous group of heritable connective tissue disorders (HCTDs) characterized by joint hypermobility, skin hyperextensibility, and tissue fragility. "People with mutation in PLOD1 suffer from so called kyphoscoliotic Ehlers-Danlos syndrome, a disorder reminiscent of other, rare types of Ehlers-Danlos with mutations in carbonic sulfotransferase 14 or dermatan-sulfate epimerase." (PMID 33028365, 2020). "The kyphoscoliotic type of Ehlers-Danlos syndrome (EDS type VIA) is due to a mutation in the PLOD1 gene." (PMID 30003082, 2018). "Notably, mutations in PLOD1 lead to a different connective tissue disease, the kyphoskoliotic type of Ehlers Danlos syndrome (EDS) (type 8)." (PMID 34169326, 2021). "The importance of lysyl hydroxylation for EDS is clearly illustrated by the fact that mutation in the PLOD1 gene, encoding LH1, cause kyphoscoliotic type 1 Ehlers-Danlos syndrome." (PMID 34849481, 2021). "A study that examined 13 patients with PLOD1 related kyphoscoliotic Ehlers Danlos syndrome (kEDS) found variable diameter of fibrils along with abnormal collagen fibre outline compared with a control group." (PMID 39629472, 2024). "The c.1116+2_1116+3insTT variant in the PLOD1 gene encoding a lysyl hydroxylase 1 enzyme which converts lysine to a hydroxylysine through hydroxylation was also previously reported in a female patient of an unknown origin with an Ehlers-Danlos syndromes (EDS) type IV." (PMID 40225931, 2024). "The kyphoscoliotic form of Ehlers-Danlos syndrome is caused by mutations in the PLOD1 gene, which encodes the enzyme procollagen-lysine 1,2-oxoglutarate 5 dioxygenase-1 (PLOD1; also known as lysyl hydroxylase 1) responsible for forming cross-links in collagens via hydroxylysine-based pyridinoline." (PMID 21527992, 2011).
gastric cancer (15 papers, 2020 to 2025). A primary or metastatic malignant neoplasm involving the stomach. "For example, in gastric cancer patients, higher PLOD1 expression is significantly associated with a shorter OS and PFS." (PMID 39767559, 2024). "Mutations or overexpression of PLOD1 were also detected in esophageal squamous cell carcinoma, gastric cancer, and colorectal cancer and associated with shorter patient survival." (PMID 33420370, 2021). "High PLOD1 mRNA expression level was observed in gastric cancer and was associated with poor patient prognosis." (PMID 31892979, 2020). "Additionally, aberrant expression of PLOD1 is associated with poorer survival in colorectal and gastric cancer patients." (PMID 39767559, 2024). "Besides, PLOD1 is also significantly overexpression in a wide range of malignancies, including esophageal squamous cell carcinoma, gastric cancer, and colorectal cancer, and is significantly associated with poor patient outcomes." (PMID 33420370, 2021). "In addition, it was recently shown that some EBNA1 variants, particularly those with the amino acid substitution T85A, can more easily bind the cellular protein Procollagen-lysine, 2-oxoglutarate 5-dioxygenase 1 (PLOD1), which is associated with gastric cancer." (PMID 36430864, 2022). "PLOD1 overexpression has been reported in gastric cancer, glioma, and osteosarcoma, where it promotes tumor growth and metastasis." (PMID 41142622, 2025). "PLOD1 is upregulated in gastric cancer tissues and promotes tumorigenesis by activating the SOX9/PI3K/Akt/mTOR pathway." (PMID 39068670, 2024). "Procollagen lysyl hydroxylase 1 (PLOD1) is highly expressed in malignant tumors such as esophageal squamous cell carcinoma, gastric cancer, and colorectal cancer." (PMID 33420370, 2021). "PLOD1 has been reported that its aberrant expression level was significantly correlated with various human cancers, including prostate cancer, gastric cancer, colorectal cancer and bladder cancer." (PMID 33503035, 2021). "Noticeably, in gastric cancer, the expression levels of PLOD1, 2 and 3 were found to be up-regulated in 10, 3 and 10 analyses, respectively, with no down-regulated analyses under the threshold." (PMID 31892979, 2020). "Not only that, high-PLOD1 expression in gastric cancer is closely correlated with poor overall survival and progression-free survival, which strongly indicated that PLOD1 acted as a reliable prognostic biomarker in cancers." (PMID 33134376, 2020). "PLOD1 upregulation promotes tumor growth and metastasis in lung and gastric cancers." (PMID 40847617, 2025). "PLOD family members (PLOD1, PLOD2, and PLOD3) were shown to be associated with poor prognosis and could act as potential biomarkers or therapeutic targets for both gastric cancer and hepatocellular carcinoma." (PMID 36820030, 2023). "Moreover, PLOD1 overexpression carries a poorer prognosis in gastric cancer." (PMID 36430864, 2022). "Procollagen-lysine,2-oxoglutarate 5-dioxygenase 1 can facilitate cell growth and aerobic glycolysis through activating the PI3K/Akt/mTOR signaling in gastric cancer cells." (PMID 39511483, 2024). "Recent studies found that high levels of PLOD1 and PLOD3 were related to short OS in gastric cancer, and high levels of PLOD1 and PLOD2 were related to poor OS in bladder cancer." (PMID 39068670, 2024). "A high level of PLOD1 expression has been documented in malignant tumors, such as BLCA, gastric cancer, glioblastoma, colorectal cancer, and esophageal squamous cell carcinoma." (PMID 39664392, 2024). "PLOD1 has been shown to promote cell growth and aerobic glycolysis by regulating the SOX9/PI3K/Akt/mTOR signaling pathway in gastric cancer." (PMID 37391802, 2023). "For example, a study found that a set of enzymes PLOD1, PLOD2 and PLOD3 involved in the hydroxylation of lysine and stabilization of collagen by crosslinks, which up-regulated expression in gastric cancer patients." (PMID 35111402, 2022).
glioma (11 papers, 2018 to 2025). A benign or malignant brain and spinal cord tumor that arises from glial cells (astrocytes, oligodendrocytes, ependymal cells). "First, we analyzed the expression and mutation of PLOD1 in gliomas and its relationship with clinicopathologic characteristics." (PMID 34040895, 2021). "PLOD1 is upregulated in osteosarcoma, gastric, breast, glioma, bladder, pancreatic, and hepatocellular cancers (HCCs), correlating with advanced tumor stages, metastasis, and reduced survival." (PMID 41373732, 2025). "High PLOD1 expression levels were found in gastrointestinal carcinoma, osteosarcoma, glioma and bladder cancer." (PMID 36090047, 2022). "The expression of PLOD1 increased with the increase of glioma grade (p < 0.001) and was higher in recurrent and secondary tumor than primary tumor (p < 0.001)." (PMID 34040895, 2021). "The results showed that the expression level of PLOD1 was higher in gliomas than normal tissues, and high expression of PLOD1 was related to poor survival which can serve as an oncogenic factor and an independent prognostic indicator for glioma patients." (PMID 34040895, 2021). "According to these prognostic signatures, we constructed a nomogram to quantitatively predict the survival of glioma patients, and the results showed that the PLOD1 expression level was the leading factor." (PMID 34040895, 2021). "The results showed that high expression of PLOD1 leads to poor prognosis, and PLOD1 is an independent prognostic factor and a novel biomarker for the treatment of glioma." (PMID 34040895, 2021). "Some previous studies revealed that PLOD1 promoted tumorigenesis and metastasis in osteosarcoma, bladder cancer and esophageal squamous cell carcinoma, while the expression and prognostic role of PLOD1 in glioma remain to be further illustrated." (PMID 34040895, 2021). "The expression level of PLOD1 was significantly higher in gliomas than in normal tissues based on the CGGA and GEO datasets, and the same results were obtained in GEPIA online analysis in both GBM and LGG." (PMID 34040895, 2021). "Both PLOD2 and PLOD3 had been reported to be highly expressed in gliomas, while the prognostic value of PLOD1 remains to be further illustrated, so we want to investigate the PLOD1 expression in glioma and its clinical implication." (PMID 34040895, 2021). "We first examined PLOD1 mRNA expression in public available glioma dataset CGGA and found that PLOD1 expression was highest in grade IV glioma and lowest in grade II." (PMID 33420370, 2021). "To analyze the relationship between the expression level of PLOD1 and the prognosis of glioma, we use the CGGA, TCGA and GEO datasets performing bioinformatics analysis." (PMID 34040895, 2021). "As we found in glioma, increased expression of PLOD1 is present in many types of cancer, and the high expression leads to short disease-related survival." (PMID 34040895, 2021). "Molecular experiments were conducted on the patient-derived glioma stem cells and found that PLOD1 expressed higher in tumor tissues and cancer cell lines of patients with GBM, especially in the MES." (PMID 33420370, 2021). "Through comprehensive univariate and multivariate Cox analysis, we found that PLOD1 was an independent prognostic factor in glioma patients." (PMID 34040895, 2021). "In this study, we found that PLOD1 expression in glioma was higher than that in normal tissues using the CGGA datasets, which was verified by the GEO datasets and GEPIA." (PMID 34040895, 2021). "It has recently been recognized that PLOD1 is overexpressed in glioma." (PMID 35250490, 2022). "In addition, the expression of PLOD1 in glioma was higher than in most cancers based on the CCLE database." (PMID 34040895, 2021). "In addition, the results from the CCLE database showed that PLOD1 expression in glioma ranked 4th among the cell lines from different cancer tissues." (PMID 34040895, 2021).